ATG5 (autophagy related 5)
Diseases named in the same sentence as ATG5 in open-access papers (continued):
Sharing a sentence is not in itself a finding about the gene and the disease.
cancer (continued). "Interestingly, our flow cytometry measurements did not detect significant changes in bulk neutral lipid levels caused by ATG5 deficiency in amino acid-starved HeLa- and MDA-MB-231 cancer cells." (PMID 37835551, 2023). "ATG2B and ATG5 suppress cancer stemness by inducing autophagy in TNBC." (PMID 36831455, 2023). "Aberrant expression of ARHGAP12, ATG5 and CNTN3 is associated with different types of carcinomas." (PMID 37026480, 2023). "However, there are studies that have shown that silencing or downregulation of autophagy-related proteins such as autophagy-related 5 (ATG5) can impair autophagy and prevent cancer cells death." (PMID 35527284, 2022). "A study demonstrated that knockout or knockdown of Atg5 and Atg7 prevents cancer cells from ferroptosis by decreasing intracellular ferrous iron levels and lipid peroxidation, indicating that autophagy may activate ferroptosis to enhance tumor immunotherapy." (PMID 36230955, 2022). "Hence silencing the Belcin1 or ATG5 expression had been shown to reduce the IR sensitivity of the cancer cells." (PMID 36172166, 2022). "However, inhibiting autophagy by deleting the gene ATG5 or ATG7 prevented RAS-mediated cancer cell proliferation." (PMID 35359388, 2022). "Similarly, silencing of prominent autophagic genes like Atg5 was able to induce radio sensitivity within radio-resistant cancer stem cell populations (prostate CSCs)." (PMID 36172166, 2022). "Additionally, cancer cells knocked down for ATG5 or beclin-1 exhibited an enhanced radiosensitivity as a consequence of the inhibition of autophagy." (PMID 35054896, 2022). "Therefore, miR-30b targeting ATG5 not only participates in the regulation of autophagy but also inhibits the proliferation and invasion of cancer cells." (PMID 35291564, 2022). "However, inhibiting autophagy via 3-methyladenine (3-MA) or ATG5 gene siRNA sensitized cancer cells to apoptosis." (PMID 35359388, 2022). "To further confirm that SRSF1-knockdown could inhibit Gefitinib-resistant cancer cell progression through activation of autophagy, we knocked down ATG5, a factor required for autophagic vesicle formation, in SRSF1-reduced Gefitinib-resistant HCC827 cells." (PMID 33664238, 2021). "Single-sample gene-set enrichment and gene functional enrichment results showed that ATG5 was correlated with some cancer-related pathways, such as phagocytosis-related genes, endocytosis-related genes, immune-related genes, EMT score, and some EMT signature-related genes." (PMID 34901004, 2021). "In addition, upregulation of ATG5 in oncogene-induced senescence induces autophagy and promotes autophagic death of cancer progenitor cells." (PMID 34903728, 2021). "Although the specific mechanism of autophagy involved in cancer cells remains largely unknown, Atg5-dependent autophagy was shown to be transiently activated early on the reprogramming process, which was blocked in Agt5−/− cells in particular." (PMID 33919790, 2021). "Herein, ATG5-mediated autophagy should be considered as factor which promotes cancer progress." (PMID 34253689, 2021). "Our results established Atg5 as an important regulatory factor during cancer metastasis." (PMID 34409736, 2021). "However, mutations of autophagy-related genes such as ATG5 and ATG7 are rare and autophagy can be activated in cancer cells under various stress conditions, indicating autophagy-independent regulation implicated in p62 expression." (PMID 33854041, 2021). "ATG5, GABARAP, ATG7, and ULK2 had a higher frequency of loss mutations in the pan-cancer analysis." (PMID 34636718, 2021). "Tang's group demonstrated that knockout or knockdown of autophagy-related 5 (Atg5) and autophagy-related 7 (Atg7) degraded ferritin in fibroblasts and cancer cells, resulting in the limitation of erastin-induced ferroptosis by decreasing intracellular ferrous iron levels and lipid peroxidation." (PMID 32256352, 2020).
cancer (continued). "Among mammal ATG proteins, Beclin-1, ATG5, ATG7, ATG12, ATG16L1 and LC3B are the most studied with respect to inflammation, and defects in autophagy are linked to many inflammatory diseases and cancer." (PMID 31969156, 2020). "Finally, autophagy has also been described as an adaptive survival mechanism for cancer cells under acidosis, in particular through the enhanced expression of autophagy-related protein 5 (ATG5)." (PMID 30941310, 2019). "Besides Beclin1 and EI24, the altered expression of several autophagy proteins such as Atg5 and UVRAG are also reported to be associated with various human cancers." (PMID 30717078, 2019). "As is confirmed that HIF1α commonly overexpresses in pejorative PCa, it’s reasonable for us to suspect that HIF1α might deteriorate PCa by accelerating autophagy and upregulating ATG5 to promote the cancer cell proliferation and migration in PCa." (PMID 31700698, 2019). "Since N-cadherin and Vimentin have been proved usually positive in various cancer metastases, we speculated the downregulation of ATG5 might impact the HIF1α-induced metastasis ability of PC-3 cells." (PMID 31700698, 2019). "ATG5 and P62, as essential autophagy-related regulatory proteins, have recently been identified as novel potential prognostic biomarkers for colorectal, breast, cutaneous, and other types of cancer." (PMID 30092789, 2018). "Notably, in our hands, autophagy inhibition with HCQ or Atg5/Atg7 RNAi sensitized cancer cells to PPI-induced cell death." (PMID 29789637, 2018). "In addition, AT-101 was shown to prevent the interaction between Bcl-2 and Beclin-1 at the endoplasmic reticulum, to decrease the levels of Bcl-2 and to increase Beclin-1 expression by inducing Beclin-1 Atg5-dependent autophagic pathway in cancer cells." (PMID 30459622, 2018). "However, with regard to the prognostic impact of ATG5 and P62 immunohistochemistry in various types of cancers, there are considerable discrepancies in the previous reports." (PMID 30092789, 2018). "In addition, gossypol prevents the interaction between Bcl-2 and Beclin-1 at the endoplasmic reticulum, decreases the levels of Bcl-2 and increases Beclin-1 expression by inducing Beclin-1 Atg5-a dependent autophagic pathway in cancer cells." (PMID 30459622, 2018). "Taken together, the expression level of ATG5 may serve as a valuable indicator for chemoresistance and prognosis of cancer patients." (PMID 29382381, 2018). "Therefore, we have decided to downregulate ATG5 via shRNA approach to assess how this modification would influence the sensitivity of cancer cells to photodynamic therapy." (PMID 29463237, 2018). "Therefore, the use of autophagy inhibitors or autophagy protein-5 (ATG5)—small interfering RNAs (siRNA) enhanced AgNPs induced cell death in cancer cells." (PMID 27649147, 2016). "For example, decreased expression of ATG5 relative to GLUT1 in a biopsy core showing predominantly stroma or only low-grade cancer may indicate the presence of nearby higher-grade cancer that was missed by the biopsy." (PMID 27152194, 2016). "Moreover, the up-regulated expression of ATG5 in cancers provides further evidence to indicate the potential role of down-regulated miR224-3p in tumorigenesis." (PMID 26536662, 2015). "In addition to the pharmacological inhibitor, we used a genetic approach by knocking down ATG5 expression using a specific siRNA and examined its effect on resveratrol-induced cancer cell death." (PMID 26067645, 2015). "Furthermore, after ATG-5 expression or aotophogy was inhibited, the cancer cells were sensitized to DPP treatment." (PMID 25329677, 2014). "Therefore, our data revealed that ATG-5 was involved in the drug resistant of DC cells, which was mainly through affect the autophagy of the cancer cells." (PMID 25329677, 2014).
cancer (continued). "Notably, integration of the BLV genome has been identified near the genes that play a role in cancer development, such as in the intergenic region of RTN4IPI and ATG5, and in the intron of the regulatory-associated protein of mTOR (RPTOR) in two B-cell lymphoma lines." (PMID 41596377, 2026). "Similarly, the glycolysis inhibitors 3-BrPA, 2-DG, lonidamine and DCA demonstrate greater cytotoxicity in ATG7 or ATG5 knockdown cancer cell lines than in the corresponding wild-type cell lines, as was evidenced by decreased viability and proliferation and increased cell death." (PMID 37887330, 2023). "The lack of ATG5 causes cancer cells to be insensitive to drug-induced autophagy." (PMID 36284209, 2023). "On this basis, after adding CAR to activate CHRM1, it was found that the previous inhibitory effect was not significantly restored, suggesting that high expression of Atg5 could be a contributing factor in the early and malignant progression of malignant tumors." (PMID 35720225, 2022). "However, the role of ATG5 in cancer has been inadequately investigated." (PMID 33926066, 2021). "In addition to this, ATG5 expression was confirmed to correlate with these clinically significant phenotypes, in conjunction with immune neoantigens and immune checkpoint gene expression profiles in pan-cancer." (PMID 33842365, 2021). "Besides, the role of CDKL3 in ESCC was studied in vitro and in vivo assays, and to exploit whether ATG5 exerts its effects on CDKL3-dependent cancer promotion." (PMID 32974198, 2020). "Furthermore, we found that BRD4 expression was negatively associated with both ATG5 and LAMP1 expression in pan-cancer patients, indicating that JQ1 increases the expression of ATG5 and LAMP1 via the suppression of BRD4 expression, subsequently inducing ferritinophagy." (PMID 30988278, 2019). "Deregulation of ATG5 may uncouple these processes and promote drug resistance in cancer cells." (PMID 25481044, 2014). "Therefore, the calpain-mediated ATG5 cleavage constitutes yet another checkpoint that may be targeted by cancer therapeutics." (PMID 23840208, 2013). "For instance, cancer-triggering stimuli may suppress calpain expression, preventing generation of truncated ATG5, resulting in decreased apoptosis and the survival of cancer cells; conversely, stimuli that promote calpain-mediated ATG5 cleavage may be used to treat cancers." (PMID 23840208, 2013). "Mechanistically, Beclin 1 interacts with key autophagy-related proteins, including ATG5 and ATG7, to facilitate the formation and maturation of autophagosomes, thereby sustaining cancer cell survival during chemotherapy." (PMID 40843353, 2025). "Our investigations into RF have demonstrated its capacity to trigger autophagy in cancer cell lines, as shown by LC3 cleavage and diminished ATG5 levels." (PMID 38540189, 2024). "PRDM1 and ATG5 are both involved in the immunity and pathogenesis of chronic infections such as CHB and cancers." (PMID 38353395, 2024). "Pterostilbene restores autophagic activity in cisplatin-resistant OSCC cells by activating autophagy-related genes, including ATG5, ATG7, and Beclin-1, through modulation of the AKT pathway, leading to enhanced cancer cell death." (PMID 39840028, 2024). "We reconfirmed the correlational analysis data with the expression of MAP1LC3B, ATG5, ATG13, and ATG14 in cancer patients, in KRAS-mut compared to KRAS-WT (p < 0.05)." (PMID 39057088, 2024). "Knockdown of Atg5 or BECN1 in cancer cells infected with bacteria significantly increases bacterial proliferation and slows down cancer cell growth." (PMID 38262996, 2024).
cancer (continued). "Some studies demonstrate that cancer cell stemness of teratocarcinoma and ovary is reduced after knocking down ATG12, ATG7 and ATG5, indicating autophagy is a stemness promoter." (PMID 37355631, 2023). "Although autophagy depletion and genetic deletion of ATG5 and ATG7 initiate tumors in mice, these interventions ultimately slow the progression of malignant tumors in tissue-specific cancer models derived from various oncogenes." (PMID 38067169, 2023). "ER stress and hypoxia increase the transcription of ULK1/ULK2, Atg5/ATG5, ATG4B, ATG13, LC3, and GABARAPL1 in several mammalian cancer cells." (PMID 35159248, 2022). "To date, there are at least three pathways that mediate ferroptosis in cancer cells: system Xc-/GSH/GPX4, FSP1/CoQ10/NAD(P)H, and ATG5/ATG7/NCOA4." (PMID 36009223, 2022). "To date, many related pathways have been found to mediate ferroptosis in cancer cells, including system Xc-/GSH/GPX4, FSP1/CoQ10/NAD(P)H, and ATG5/ATG7/NCOA4 pathways, which are considered potential therapeutic targets, especially for the treatment of cancers." (PMID 36009223, 2022). "Curcumin has been shown to upregulate the expression of autophagy‐related proteins, including ATG5 and ATG2B and induce overall autophagy flux in human cancers." (PMID 35029026, 2022). "In this study, we demonstrated increased autophagy flux induced by over-expression of ATG5 in LUSC, which was regarded as an cancer promoting elements." (PMID 34253689, 2021). "In order to verify if the anti-cancer effect of SRT2183 is dependent on the autophagy, we knocked down autophagy related 5 (ATG5) and autophagy related 7 (ATG7), two master regulators of autophagy, by shRNA-lentivirus." (PMID 33223507, 2020). "One drawback of our study is that it solely used SW480 cells to define the role of ATG5 and RAB21 in cancer cell hyperproliferation." (PMID 31383875, 2019). "Inhibition of autophagy by 3-MA and lentivirus-derived Atg5 shRNA suppressed the cell migration and invasion in presence of FSS, suggesting FSS plays an important role in metastasis of cancer cells through autophagy pathway." (PMID 30663937, 2019). "One study showed that the inhibition of autophagy by silencing of Beclin 1 and ATG5 decreased hypoxia-induced activation of STAT3 and restored cancer cell sensitivity to T-cell cytotoxicity." (PMID 30400561, 2018). "Our results are consistent with other reports that autophagy inhibition by CQ or other autophagy inhibitor (e.g., ATG-5 siRNA and ATG-7 siRNA) induces cell death in cancer cell types." (PMID 24581180, 2014). "The discovery of the ATG5-FADD interaction suggests that decreased expression of either ATG5 or FADD would impact both, autophagy and apoptosis, and therefore, these proteins likely play important and complex roles in cancer development." (PMID 23840208, 2013). "We thus hypothesize that CD46/TREM1 may contribute to the inflammation-cancer transformation in OSCC by activating the PI3K-AKT-mTOR pathway and subsequently inhibiting autophagy, as indicated by downregulated LC3B/ATG5." (PMID 41415031, 2025). "Similarly, pterostilbene restores autophagic activity in cisplatin-resistant OSCC cells by activating autophagy-related genes, including ATG5, ATG7, and Beclin-1, through modulation of the AKT pathway, leading to enhanced cancer cell death." (PMID 39840028, 2024). "Silencing the autophagy genes, such as ATG5, ATG7, and BECN1, could inhibit the DAMP release from mitoxantrone or oxaliplatin-treated cancer cells and subsequently impair the antitumor immunity." (PMID 36814780, 2023). "Similarly, deletion of ATG5 and ATG7 favors the maintenance of an increased level of glycolysis and glycolytic capacity in human cancer cell lines." (PMID 37887330, 2023). "This study found that NORAD was activated due to an increase in oxidative stress, and this lncRNA upregulated ATG5 and ATG12 levels and may be regarded as a useful biomarker in this cancer to predict oxaliplatin resistance." (PMID 36983973, 2023).
cancer (continued). "In addition, RTA dh404 promoted or repressed genes related to autophagy in cancer cells, including four genes (SQSTM1(p62), MAP1LC3B(LC3B), ATG5, and ATG12) in GBM8401 cells and two genes (SQSTM1 (p62) and MAP1LC3B (LC3B)) in U87MG cells." (PMID 36835414, 2023). "Additionally, others have shown that also glucose starvation induces ATG5 and LC3-dependent microautophagy in cancer." (PMID 37255933, 2023). "It was indeed reported that Beclin-1, but also ATG5 and ATG3, are caspase-8 substrates in vitro, and that after death receptor activation in several cancer cells, the subsequent downregulation of autophagic flux is partly due to caspase-8-dependent cleavage of these autophagic proteins." (PMID 36418547, 2023). "Indeed, overexpression of autophagic proteins (autophagy related protein 5 (ATG5), Beclin and light chain 3 alpha/beta (LC3A/B)) in three cancer cell lines was detected during EMT, which was diminished in YWHAG‐knockdown cells." (PMID 37759388, 2023). "Nevertheless, given that malignant tumors failed to form in long‐lived mosaic Atg5 knockout mice, the transient inhibition of autophagy appears to increase the risk of cancer relative to the continuous inhibition of autophagy." (PMID 35689420, 2022). "TGFB1 secretion is abolished in fibroblasts and macrophages where key autophagy regulators such as ATG5 and ATG7 are ablated, hinting that targeting TGFB1 release by SA may be beneficial in cancer." (PMID 36601581, 2022). "Furthermore, treatment with curcumin led to attenuation of cancer stemness in TNBC CSCs; the expression of ATG5 and ATG2B was enhanced and there was an increase of autophagy flux." (PMID 35029026, 2022). "The mutations with mononucleotide repeats have been found in ATG2B, ATG5, ATG9B, and ATG12 genes in gastric and colorectal cancers, which may be involved in cancer development by dysregulating autophagy." (PMID 34443541, 2021). "Interestingly, ChIP-seq data with NRF1 in 4 different cancer cell lines depicted strong enrichment in close proximity of both ATG7 and ATG5 TSSs." (PMID 34458153, 2021). "Furthermore, ATG16L2 is overexpressed in several cancers and competes with ATG16L1 for binding to ATG5 resulting in proteasomal degradation of ATG16L1 and disruption of autophagy." (PMID 34706732, 2021). "In metastatic HCC, miR-30a mediates Beclin 1 and Atg5-dependent autophagy, which confers anoikis resistance of HCC cells 50, suggesting important roles of miRNAs in the regulation of autophagy and anoikis resistance in cancer." (PMID 33995620, 2021). "Previous studies showed that Sirt1 might regulate autophagy due to deacetylation of Atg5, Atg7, or LC3 in cancer cells, MEFs, germ cells, and stem cells." (PMID 33723227, 2021). "Treatment of ATG5−/− cells with milk-derived EVs or Cas9 cells with the autophagy inhibitor Bafilomycin A did not increase the cell viability of cancer cells." (PMID 34168137, 2021). "In a recent study by Saleh and coworkers, neither shRNAs against ATG5 nor BAF A1/HCQ treatment prior to the subsequent exposure to chemotherapeutics or radiation affected ability of cancer cells to induce senescence or recover from it." (PMID 35127467, 2021). "In fact, we found in a previous study that serum deprivation decreases the complexation between survivin and ATG12/ATG5 (possibly to upregulate autophagy), but not caspase-3 (concurrently maintains apoptosis inhibition), in human cancer cells." (PMID 32019552, 2020). "Additional connections between changes on these genes and cancer are those of ATG5 in multiple myeloma or non-medullary thyroid cancer." (PMID 33147747, 2020). "Of note a whole-body mosaic Atg5 knockout mouse model has been previously reported to only develop liver adenomas but without any malignant tumours." (PMID 31949142, 2020). "Literatures showed that targeting autophagy-related proteins LC3, ATG5, ATG7, SQSTM1, and Akt/mTOR (mammalian target of rapamycin) pathway could regulate autophagy initiation in cancer cells." (PMID 31309361, 2019).